NRG1 (neuregulin 1)
Diseases named in the same sentence as NRG1 in open-access papers (continued):
Sharing a sentence is not in itself a finding about the gene and the disease.
schizophrenia (continued). "This association of NRG1 with schizophrenia was confirmed by the same group in a Scottish population and by an independent study in a large sample of unrelated Welsh patients." (PMID 22937274, 2011). "In the current study, we attempt toexamine the association of SNP8NRG241930 from the NRG1 gene with schizophrenia inan Iranian population." (PMID 23508206, 2011). "The Nrg1 gene has also been identified as a candidate schizophrenia susceptibility gene, and levels of the Type III isoform were reported to be decreased in post-mortem tissue of some schizophrenics." (PMID 21949864, 2011). "Genetic studies suggest that the genomic mutation or polymorphism for EGF, NRG1 and their receptors (ErbBs) is associated with schizophrenia risk." (PMID 22022452, 2011). "Single nucleotide polymorphisms of the NRG1 gene have been associated with schizophrenia and bipolar disorder." (PMID 22028923, 2011). "Neuregulin-1 (NRG1) is one of the susceptibility genes for schizophrenia and implicated in the neurotrophic regulation of GABAergic and dopaminergic neurons, myelination, and NMDA receptor function." (PMID 21151609, 2010). "This abrogated cleavage of NRG1, which is genetically linked to schizophrenia, has also been implicated in schizophrenia-like phenotypes described in BACE1-/- mice." (PMID 20731874, 2010). "Neuregulin1 (NRG1)-ErbB signaling has been implicated in the pathogenesis of cancer and schizophrenia." (PMID 20520724, 2010). "Our findings provide a potential mechanism for the impact of COMT on NRG1-induced adhesion and migration and also possibly for the association of these genes with schizophrenia and cancer." (PMID 20520724, 2010). "These include a number of genes previously associated with schizophrenia including the susceptibility gene neuregulin 1 (NRG1)." (PMID 19457239, 2009). "In the case of schizophrenia, a population-based analysis has revealed four genes, DAAO (DAO), DAOA, DTNBP1 and NRG1, to be associated with the schizophrenia." (PMID 19379523, 2009). "Neuregulin-1 (Nrg1) represents the best characterized ErbB4 ligand and has been shown to be implicated several diseases, including cancer and schizophrenia." (PMID 18620601, 2008). "Several genes, e.g., DISC1 and NRG1, which have been repeatedly shown to be associated with susceptibility to schizophrenia, are involved in GSK-3/Wnt regulatory pathways." (PMID 18702828, 2008). "For example, neuregulin 1 (NRG1) is a potential susceptibility gene for schizophrenia, and alterations in NRG1-ErbB signaling occur in the prefrontal cortex of schizophrenic patients." (PMID 18335055, 2008). "NRG1 itself has been associated with schizophrenia in the Icelandic DeCODE population and in other studies, with accelerated lobar atrophy, and with bipolar disorders." (PMID 17903297, 2007). "This provides indirect evidence supporting NRG1 association with schizophrenia and a role for aberrant neuregulin signalling in this disorder." (PMID 17598910, 2007). "In this manuscript we present confirmation of earlier published associations between schizophrenia and the genes NRG1 and ERBB4." (PMID 17598910, 2007). "If these findings in immune cells are conserved in neuronal cell processes, they would argue that a mechanism of the NRG1 genetic association with schizophrenia involves the molecular biology of cell adhesion." (PMID 18159252, 2007). "Nonetheless, several recent publications report an association between schizophrenia and ErbB4, one of the receptors for NRG1." (PMID 17598910, 2007). "This study confirms previously published associations between schizophrenia and NRG1 and ERBB4, and points to three other members of the NRG and ERBB gene families (EGFR, NRG2 and NRG3) as potential schizophrenia susceptibility genes." (PMID 17598910, 2007). "The association studies reported thus far strongly suggest a true effect of NRG1 as a susceptibility gene for schizophrenia." (PMID 17598910, 2007).
schizophrenia (continued). "Evidence of genetic association between the NRG1 (Neuregulin-1) gene and schizophrenia is now well-documented." (PMID 17598910, 2007). "Neuregulin-1 (NRG1) is a putative schizophrenia susceptibility gene involved extensively in central nervous system development as well as cancer invasion and metastasis." (PMID 18159252, 2007). "Although NRG1 rs3294999 is considered a risk gene for schizophrenia, the present study found few statistically significant differences in reasoning and cognitive flexibility scores between patients with onset psychosis and chronic patients when comparing its genotype." (PMID 39518545, 2024). "Deficiencies in NRG1 are associated with Hirshprung’s disease, leading to poor innervation of the gut, as well as abnormal brain development and mental disorders like bipolar disorder or schizophrenia." (PMID 39210279, 2024). "Interestingly, two susceptible genes linked to schizophrenia include NRG1, the gene encoding neuregulin-1 (NRG1), and ERBB4, which encodes receptor tyrosine kinase ERB-B4." (PMID 38563502, 2024). "Among genetic polymorphisms, neuregulin 1 (NRG1) was studied as a risk factor for schizophrenia." (PMID 39062492, 2024). "This study underscores the role and regulation of nNOS within a specific subset of GABAergic interneurons, offering insights into the pathophysiological mechanisms of schizophrenia, given the association of Nrg1, Erbb4, Pi3k, and Nos1 genes with this mental disorder." (PMID 38396027, 2024). "Another candidate variant of susceptibility for schizophrenia is the rs3924999 variant of NRG1." (PMID 39518545, 2024). "Murine models showed a significant impact of NRG1 in spatial cognition and social behavior, while other studies found an association with attention deficits and visual memory deficits in schizophrenia patients." (PMID 39518545, 2024). "Moreover, a recent study evaluated several proteins of PSD and discovered 10 rare missense mutations in PSD protein-related genes, including NRG1 as susceptibility factors for schizophrenia." (PMID 36831241, 2023). "Thus, it has been linked with the potential of developing schizophrenia as NRG1 expressed proteins are associated in synaptic plasticity, myelination and neuronal migration." (PMID 36692676, 2023). "It is known that neuregulin-1 is both associated with schizophrenia and glutamatergic transmission." (PMID 38004423, 2023). "Nrg1 TM HET mice exhibit cognitive deficits in novel object recognition and recall of contextual fear conditioning, while in clinical populations, NRG1 SNPs and serum NRG1β1 concentration are linked with poorer cognitive ability in individuals with schizophrenia." (PMID 37233814, 2023). "Polymorphism of genes such as dysbindin, DICS1, and NRG1 has also been reported in schizophrenia." (PMID 36692676, 2023). "Neuregulin 1 (NRG1) is well-established risk gene for schizophrenia [review:], and a missense mutation in the transmembrane domain of NRG1 is associated with schizophrenia." (PMID 37233814, 2023). "Previous studies have reported alterations in the expression of plasticity-associated genes such as BDNF, NGF, VEGF, and NRG1 in the blood of individuals with schizophrenia, which may provide new evidence for synaptic plasticity dysfunction in schizophrenia." (PMID 37990254, 2023). "Nrg1 (Neuregulin 1) is one of the widely studied susceptible genes for schizophrenia." (PMID 38136627, 2023). "NRG1 was first identified as a major susceptibility gene in schizophrenia." (PMID 35606871, 2022). "NRG1 and its receptor ErbB4 have been linked to abnormal cortical function in schizophrenia." (PMID 36460658, 2022). "The ERBB4 and NRG-1 genes have been implicated as risk genes for the development of schizophrenia." (PMID 36119496, 2022). "Moreover, mutant mice carrying mutations in the NRG-1 or erbB4 gene show schizophrenia-like behaviors such as disruption of PPI, latent inhibition and cognitive deficits." (PMID 36620856, 2022).
schizophrenia (continued). "Here, we investigated if adolescent CBD treatment could prevent the development of schizophrenia-relevant behaviors in Nrg1 TM HET males, and also reduce susceptibility to an acute THC challenge in early adulthood." (PMID 36406747, 2022). "It is known that dendritic spine deficits might be a significant hallmark of schizophrenia, and in mice mimicking high levels of NRG1 (ctoNrg1), spine development deficits have also been observed." (PMID 35682647, 2022). "From these findings, dysfunction of NRG-1/erbB4 signaling may be associated with development of schizophrenia." (PMID 36620856, 2022). "In addition, dysregulated expression of Nrg1, including elevation of expression of Nrg1, increases disease susceptibility and has been found in studies of post-mortem brain tissue from schizophrenia patients." (PMID 35562880, 2022). "Additionally, NRG1 polymorphisms have been shown to be associated with schizophrenia, Alzheimer's disease, Hirschsprung's disease, TC, and other carcinoma development and metastasis." (PMID 35558387, 2022). "NRG1/ErbB4 signaling is strongly linked to working memory dysfunction, and several recent studies have investigated its relevance as a candidate therapeutic pathway for schizophrenia." (PMID 35876932, 2022). "Moreover, one of these variants is associated with an increased risk of schizophrenia in people carrying the Icelandic NRG-1 risk haplotype." (PMID 36119496, 2022). "In sum, the data presented here demonstrate mechanisms underlying how Nrg1 dysregulation impairs brain function, which might provide insight into the pathophysiological mechanisms of schizophrenia." (PMID 33436636, 2021). "Similarly, knocking out the NRG1 gene, which is implicated in schizophrenia, is also used to study schizophrenia-like behaviors and circuit dysfunctions." (PMID 33613338, 2021). "Neuregulin 1 (Nrg1) is genetically associated with schizophrenia in diverse populations." (PMID 33436636, 2021). "In sum, our results demonstrate mechanisms underlying cortical disinhibition related to schizophrenia and raise a possibility that relevant brain disorders may benefit from intervention to restore NRG1 signaling and GABAergic function." (PMID 33436636, 2021). "The direct and chronic disturbance of NRG1/ErbB4 signal transmission, such as the mutation of NRG1 or ErbB4 gene in some schizophrenia patients, can lead to the abnormality of glutamatergic synapses and nerve fibers, thus leading to developmental and functional abnormalities." (PMID 33897409, 2021). "For the NRG1 rs35753505 genotype, fractional anisotropy in the anterior cingulum of patients with schizophrenia with the T allele is significantly lower than that of patients with schizophrenia with CC genotype and healthy controls with T allele." (PMID 34566604, 2021). "Hypofunction of the NMDA receptor is hypothesized to be a mechanism underlying cognitive dysfunction in individuals with schizophrenia and altered NRG1-ErbB4 signaling may contribute to NMDA receptor hypofunction seen in these patients." (PMID 34393751, 2021). "Moreover, NRG1 risk variants linked to schizophrenia have also been associated with reduced white matter density and integrity." (PMID 32425837, 2020). "Interestingly, we previously found that NRG1/ErbB4 (susceptibility genes of schizophrenia) signaling is critical for EAAC1 expression and function." (PMID 32818073, 2020). "In the same cohort of patients, the authors also found that the neuregulin-1 (NRG1) rs35753505 polymorphism, which has been studied extensively for its potential role in the pathogenesis of schizophrenia, further decreased auditory hallucinations when present with COMT Val/Val." (PMID 32742620, 2019).
schizophrenia (continued). "Although the overall results generally supported the association between NRG1 rs6994992 and schizophrenia, there has also been evidence suggested an ethnic difference in the relationship between NRG1 rs6994992 and schizophrenia, with the association mainly being present in the European populations." (PMID 31649580, 2019). "Moreover, post-mortem studies have revealed a selective loss of PV+ interneurons in people with schizophrenia and overexpression of Neuregulin 1, a leading schizophrenia susceptibility gene, is associated with a reduction of NMDARs on PV+ cells." (PMID 31657720, 2019). "Considering this fact, to further validate whether NRG1 rs6994992 underlies the genetic link between schizophrenia and creativity, it is necessary to reevaluate the association between NRG1 rs6994992 and creativity in other populations." (PMID 31649580, 2019). "Besides NRG1 rs6994992, 10 other schizophrenia risk variants were also investigated in this study and the results showed that only ZNF536 rs2053079 was nominally associated with creativity." (PMID 31649580, 2019). "Moreover, the main receptor for NRG1 signaling, ErbB4, itself a schizophrenia risk gene (Schizophrenia Working Group of the Psychiatric Genomics Consortium, 2014), is expressed in PV+ and CCK+ GABAergic interneurons but not in glutamatergic pyramidal cells." (PMID 29740596, 2018). "Numerous human genetic studies have identified NRG1 as a schizophrenia susceptibility gene." (PMID 29844389, 2018). "Furthermore, genetic linkage and association studies led to the identification of two additional susceptibility factors related to schizophrenia, such as neuregulin-1 (NRG1) and its receptor ErbB4." (PMID 30061532, 2018). "Interestingly two NRG1 schizophrenia-associated SNPs from the original Icelandic haplotype occur in regions that show predicted binding sites for SRF that are abolished by presence of the SNPs." (PMID 29520222, 2018). "To better understand whether certain behavioral changes caused by anti-NRG1 treatment could be a result of altered signaling in the CNS, we evaluated behaviors more directly related to CNS changes and/or schizophrenia itself." (PMID 29844389, 2018). "Of these pathways, schizophrenia appears to have to strongest link to the Nrg/ErbB pathway, and SNPs in several of the genes encoding Nrg (NRG1, NRG2, NRG3, and NRG6) and all of the genes encoding ErbB receptors (EGFR, ERBB2, ERBB3, and ERBB4) have been linked to schizophrenia." (PMID 30618607, 2018). "Furthermore, a single-nucleotide polymorphism associated with cannabis dependence is located in the neuregulin 1 (NRG1) gene, which is a susceptibility gene for schizophrenia." (PMID 29467679, 2018). "Thus, we have conducted an updated comprehensive meta-analysis of the association between NRG1 genetic variation and schizophrenia, including single markers across the entire gene as well as haplotypes." (PMID 28094814, 2017). "NRG1 is widely distributed in the frontal cortex, midbrain, and cerebellum, and significantly associated with endophenotypes of schizophrenia via regulating myelination, neuronal migration, and function of neurotransmitter receptors." (PMID 28993723, 2017). "Interestingly, overexpression of secreted Nrg1 by Bace1 cleavage (Nrg1-ntfβ) in mice was sufficient to cause schizophrenia-like phenotypes." (PMID 28993723, 2017). "Double deficiency of Akt1 and Nrg1 can result in the impairment of social cognitive functions, which might be pertinent to the pathogenesis of schizophrenia-related social cognition which related to schizophrenia." (PMID 29156812, 2017). "According to these Nrg1 genetic models, it is possible that dysfunction of NRG1 or NRG1/ErbB4 signaling may affect neural development and synaptic plasticity by disturbance of glutamatergic or GABAergic systems implicated in schizophrenia." (PMID 28993723, 2017).
schizophrenia (continued). "Reconciling contradictory data concerning the association between NRG1 and LI performance involves acceptance of differing underlying neural mechanisms governing the effects of mutation of Nrg1 on attentional tasks of relevance to schizophrenia." (PMID 28338897, 2017). "Thus, arguably a more thorough evaluation of NRG1’s association with schizophrenia requires examination of variation beyond SNPs." (PMID 28094814, 2017). "We therefore summarized that schizophrenia-like behaviors are related to various Nrg1 mutations." (PMID 28993723, 2017). "NRG1 isoforms differ in domain structure and expression levels in various tissues/cells during brain development and, later, in adulthood; isoform-specific roles and properties, particularly in relation to the NRG1-schizophrenia association, remain poorly understood." (PMID 27725886, 2016). "Disrupted in Schizophrenia 1 (DISC1) is another putative schizophrenia risk gene, and many lines of evidence suggest that it may functionally and/or physically interact with the NRG1-ErbB4 signalling pathway." (PMID 27847649, 2016). "NRG1 proteins are ligands for ErbB receptor tyrosine kinases; this, in turn, activates intracellular signalling pathways that are known to play a prominent role in diverse developmental processes implicated in schizophrenia." (PMID 27725886, 2016). "Neuregulin-1 (NRG1) is one of candidate genes for schizophrenia susceptibility." (PMID 26935991, 2016). "Interestingly, animals with transmembrane Neuregulin 1 mutation, representing a genetic glutamatergic schizophrenia model, showed similar startle amplitude and PPI compared to their wild type like littermates." (PMID 27877130, 2016). "Taken together, there is strong evidence from NRG1 overexpression and knockout studies in mice for the association of altered developmental NRG1-ErbB4 signalling with schizophrenia; however, relatively few studies have addressed the role of BACE1-cleaved NRG1 in the mature brain." (PMID 27456313, 2016). "Furthermore, a risk pathway has been recently reported in schizophrenia that involves NRG1, the ErbB4 receptor isoform CYT-1 and the p110δ catalytic subunit of the IA PI3K class." (PMID 26877878, 2016). "The genetic model is based on neuregulin 1, a susceptibility gene for schizophrenia." (PMID 27877130, 2016). "NRG1/ErbB signaling has recently been implicated in several neuropsychiatric disorders, such as schizophrenia and bipolar disorder, because of its importance in development and function of neural circuitry, relevant to behavioral deficits and genetic association with those diseases." (PMID 27377368, 2016). "I have used the ErbB4-/- HER4heart KO mice to study the neurodevelopmental insults associated to deficiencies in the NRG1-ErbB4 signaling pathway and their potential implication with brain disorders such as schizophrenia, a chronic psychiatric disease affecting 1% of the population worldwide." (PMID 26733804, 2015). "In addition, we investigate the regulation of high-frequency (gamma) electrophysiological oscillations in this mutant mouse to associate molecular changes in Nrg1 with a schizophrenia-relevant neurophysiological profile." (PMID 25992564, 2015). "For instance, neuregulin 1 (Nrg1) has been identified as a susceptibility gene for schizophrenia." (PMID 25693194, 2015). "NRG1 is involved in many aspects of brain development, including neuronal maturation and variations in this gene have been shown to be associated with increased risk for mental disorders, particularly schizophrenia." (PMID 25897834, 2015). "In addition, a recent report shows that first-degree relatives of patients with schizophrenia show a decrease in VS activation during reward anticipation, which is also influenced by a polymorphism in the neuregulin-1 gene." (PMID 25477792, 2014).